GATM (glycine amidinotransferase)
Description:
Transamidinase that catalyzes the transfer of the amidino group of L-arginine onto the amino moiety of acceptor metabolites such as glycine, beta-alanine, gamma-aminobutyric acid (GABA) and taurine yielding the corresponding guanidine derivatives. Catalyzes the rate-limiting step of creatine biosynthesis, namely the transfer of the amidino group from L-arginine to glycine to generate guanidinoacetate, which is then methylated by GAMT to form creatine. Provides creatine as a source for ATP generation in tissues with high energy demands, in particular skeletal muscle, heart and brain (Probable).
Synonyms: AGAT; AT; CCDS3; FRTS; FRTS1; RFS
Tractability: Small molecule: a structure with a bound ligand is known; it has a binding pocket of medium quality. Antibody: UniProt places it where antibodies can reach, with medium confidence. PROTAC: its protein half-life has been measured.
Safety:
Unwanted effects reported when the protein is acted on. In parentheses: how it was acted on, where the effect was seen, and who reports it.
myopathy (source: ClinPGx)
Gene: Protein-coding gene on chromosome 15 (45,361,124 to 45,402,327, reverse strand). Ensembl gene ENSG00000171766.
Subcellular location: Mitochondrion inner membrane (Isoform 1); Cytoplasm (Isoform 2)
Subcellular location (Human Protein Atlas): Mitochondria
Pathways (Reactome):
Metabolism: Creatine metabolism
Gene Ontology:
Molecular function: amidinotransferase activity; glycine amidinotransferase activity; protein binding
Biological process: creatine biosynthetic process; learning or memory; muscle atrophy; positive regulation of cold-induced thermogenesis
Cellular component: extracellular exosome; mitochondrial intermembrane space; mitochondrion; cytoplasm; mitochondrial inner membrane
Genetic constraint (gnomAD): Loss-of-function variants: 19 observed, 46.67 expected, observed/expected ratio (o/e) 0.41, 90% interval 0.28 to 0.6. The upper end of that interval is the gene's LOEUF score, 0.6, which puts it in group 2 of 6, group 1 being the genes least tolerant of losing a copy. Missense variants: 367 observed, 503.21 expected, observed/expected ratio (o/e) 0.73, 90% interval 0.67 to 0.8. Synonymous variants: 158 observed, 173.95 expected, observed/expected ratio (o/e) 0.91, 90% interval 0.8 to 1.04.
Gene-disease validity (ClinGen):
ClinGen rates the evidence that GATM causes each of these diseases.
AGAT deficiency (autosomal recessive): Definitive. L-Arginine:glycine amidinotransferase (AGAT) deficiency is a very rare type of creatine deficiency sydrome characterized by global developmental delay, intellectual disability, and myopathy.
Fanconi renotubular syndrome 1 (autosomal dominant): Moderate.
Homologues: Orthologues: chimpanzee GATM (99% identical), macaque GATM (98% identical), dog GATM (96% identical), mouse Gatm (96% identical), rat Gatm (96% identical), pig GATM (95% identical), guinea pig GATM (93% identical), rabbit GATM (89% identical), tropical clawed frog gatm (82% identical), zebrafish gatm (79% identical).
Diseases named in the same sentence as GATM in open-access papers:
GATM is named in the same sentence as 86 diseases in open-access papers, as found by Europe PMC text mining. Sharing a sentence is not in itself a finding about the gene and the disease. The quoted sentences say what the papers report.
Obesity (13 papers, 2017 to 2026). Accumulation of substantial excess body fat. "Transgenic mice depleted of CKB, CKMT1B, and GATM showed impaired creatine biosynthesis capacity affecting the murine body weight and resulting in a susceptibility to obesity." (PMID 37101650, 2023). "The CDSs of CKB, CKMT1B, and GATM were subsequently screened for variants in 192 children and adolescents with severe obesity as well as 192 healthy-lean controls." (PMID 37101650, 2023). "Creatine availability depends on glycine amidinotransferase (GATM), the rate-limiting enzyme in creatine synthesis; adipose-specific GATM deletion impairs diet-induced thermogenesis, promotes obesity, and disrupts glucose homeostasis." (PMID 41596403, 2026). "A recent publication from the same group showed that an adipose tissue specific knockout of glycine amidinotransferase, the rate limiting enzyme for creatine biosynthesis, made mice prone to diet-induced obesity." (PMID 34832860, 2021). "Moreover, GATM in adipocytes was proved to be required for obesity-driven tumor progression." (PMID 36319832, 2022). "For CKB, CKMT1B and GATM, subsequent analyses revealed gene expression differences between VAT and SAT in 1,448 adipose tissue donors with obesity." (PMID 37101650, 2023). "In a recent study, on an obesity accelerated model of BC, a transcriptomic analysis revealed marked overexpression of glycine amidinotransferase (GATM) in cancer adipocytes, but not in normal (contralateral) ones." (PMID 37561190, 2023). "Considering the inverse correlations of CKB with CKMT1B and GATM in visceral and subcutaneous adipose tissue, we subsequently performed between-subject comparisons of non-obese participants and individuals with obesity from the LOBB for all three genes studied." (PMID 37101650, 2023). "Based on these data, we analyzed correlations between CKB, CKMT1B, and GATM expression levels and specific metabolic and anthropometric parameters in both VAT and SAT of participants with and without obesity." (PMID 37101650, 2023). "By analyzing RNA-seq data of VAT and SAT of 1,479 individuals (1,448 with obesity and 31 non-obese) of the Leipzig Obesity Biobank, we detected that all three genes of interest (CKB, CKMT1B and GATM) showed positive correlations with each other in visceral fat." (PMID 37101650, 2023).
Creatine deficiency syndromes (11 papers, 2019 to 2025). "We also obtained cells from a patient with homozygous GATM mutations associated with creatine deficiency syndrome (Coriell # GM27955) (GATM−/−)." (PMID 39544690, 2024). "Creatine deficiency syndromes (CDS), caused by mutations in GATM (AGAT), GAMT, and SLC6A8, mainly affect the central nervous system (CNS)." (PMID 38745894, 2024).
heart failure (11 papers, 2012 to 2025). Inability of the heart to pump blood at an adequate rate to meet tissue metabolic requirements. "GATM converts taurine and arginine into phosphagen taurocyamine, which, together with uridine, stabilizes the ETC and improves heart failure; all these metabolites were altered in FGF21-deficient serum." (PMID 40998786, 2025). "Increased GATM expression and creatine synthesis have been reported in the myocardium of patients with heart failure." (PMID 40836955, 2025). "Of particular note, heart failure patients with decreased circulating hArg also had an increased GATM expression in the left ventricle that was normalized after mechanical unloading and recovery of the left ventricle." (PMID 37834229, 2023). "GATM and STC1 have been among the top loci in genome-wide association studies of chronic kidney disease, and have also been implicated in heart failure." (PMID 23145134, 2012). "In humans and mice, L-arginine:glycine amidinotransferase (AGAT) and its metabolites homoarginine (hArg) and creatine have been linked to cardiovascular disease (CVD), specifically myocardial infarction (MI) and heart failure (HF)." (PMID 35332188, 2022). "L-arginine:glycine amidinotransferase (AGAT; EC: 2.1.4.1) and its metabolites homoarginine (hArg) and creatine play an important role in cardiovascular disease (CVD) such as myocardial infarction (MI), heart failure (HF) and ischemic stroke." (PMID 35332188, 2022).
Fanconi syndrome (5 papers, 2021 to 2024). "Future studies are needed to compare the levels of plasma and urine GAA among patients with GATM‐FS and those with Fanconi syndrome from other causes and with carriers of variants associated with AGAT deficiency." (PMID 39544690, 2024). "Compared with the EHHADH-linked Fanconi’s syndrome, the clinical situation of patients carrying those GATM mutations is quite the opposite: The symptoms typically found in Fanconi’s syndrome are rather mild, e.g., vitamin d-resistant rickets is absent or very mild." (PMID 34349672, 2021). "GATM protein is a renal proximal tubular enzyme involved in the creatinine biosynthetic pathway, and recent studies have shown that fully penetrant heterozygous mutations in the GATM gene lead to intra-mitochondrial fibrillary deposition and clinical manifestations of Fanconi syndrome and CKD." (PMID 33783510, 2021).
Stroke (5 papers, 2020 to 2025). Sudden impairment of blood flow to a part of the brain due to occlusion or rupture of an artery to the brain. "l-arginine:glycine amidinotransferase (AGAT) and its metabolites homoarginine (hArg) and creatine have been linked to stroke pathology in both human and mouse studies." (PMID 32182846, 2020).
chronic kidney disease (4 papers, 2012 to 2023). Impairment of the renal function secondary to chronic kidney damage persisting for three or more months. "We further recommend that adult patients showing signs of RFS and chronic kidney disease should also be screened for GATM variants." (PMID 36148635, 2023). "As GATM is a relatively new disease gene, we expect that there may be patients with chronic kidney disease, or end‐stage kidney failure harbouring variants in GATM." (PMID 36148635, 2023). "This study validated two loci previously reported at glycine amidinotransferase (GATM) and hemoglobin beta (HBB) loci that are associated with chronic kidney disease." (PMID 36388767, 2022). "For example, in the case of chronic kidney disease, CONTENT implicated GATM—a gene thought to be involved with kidney disease and GFR levels—however, the significant association was within the thyroid." (PMID 36171194, 2022).
Intellectual disability (4 papers, 2012 to 2025). "Biallelic pathogenic GATM variants result in AGAT deficiency, which causes global developmental delay, cognitive dysfunction, intellectual disability, and muscle weakness." (PMID 39544690, 2024).
pancreatic cancer (4 papers, 2023 to 2025). "Consistent with this, our team recently reported that during liver metastasis of pancreatic cancer, enhancer reprogramming promotes glycine amidinotransferase (GATM)-mediated guanidinoacetate metabolism." (PMID 40032852, 2025). "Transfection of the gRNAs targeting the candidate enhancer resulted in significant downregulation of GATM expression in pancreatic cancer cells." (PMID 37370109, 2023). "To fully evaluate the promoting role of GATM in PDAC metastasis, we chose pancreatic cancer cell lines with high GATM protein expression and knocked down the expression of GATM." (PMID 37370109, 2023). "To investigate the genome-wide changes in H3K4me3 and H3K27ac, we performed CUT&RUN analysis in pancreatic cancer cells after GATM knockdown and GAA rescue treatment." (PMID 37370109, 2023). "Next, we explored the role of GATM-mediated de novo GAA synthesis in pancreatic cancer metastasis." (PMID 37370109, 2023). "We next validated the role of GATM in promoting the liver metastasis of pancreatic cancer in vivo." (PMID 37370109, 2023). "However, we did not observe decreases in metabolites involved in the creatine-phosphagen system in pancreatic cancer cells after GATM knockdown or increases in those metabolites in the plasma of mice fed the GAA diet." (PMID 37370109, 2023). "Furthermore, c-Myc overexpression in pancreatic cancer cells with GATM knockdown restored HMGA1 and HMGA2 expression." (PMID 37370109, 2023). "Model 3 primarily includes CARNS1, CNDP1, GATM, and ABAT, which are mainly distributed in tumors, particularly pancreatic cancer and breast cancer." (PMID 36914737, 2023). "After GATM knockdown, the intracellular GAA level was decreased and pancreatic cancer cell migration was significantly suppressed." (PMID 37370109, 2023). "However, the roles and mechanisms of GATM and GAA in pancreatic cancer metastasis are incompletely elucidated." (PMID 37370109, 2023). "However, metastatic pancreatic cancer cells with high ASS1 and GATM expression maintained higher levels of intracellular arginine and GAA than those with low ASS1 and GATM expression." (PMID 37370109, 2023). "In addition, we measured the level of acetyl-CoA in pancreatic cancer cells but did not observe a significant change after GATM knockdown or GAA treatment." (PMID 37370109, 2023). "However, we did not obtain definitive and consistent evidence that GATM could promote the proliferation of these pancreatic cancer cell lines." (PMID 37370109, 2023).
renal failure (4 papers, 2013 to 2026). "GATM variants should be routinely tested for in cases of idiopathic RFS even in the absence of renal failure which develops after initial presentation." (PMID 36148635, 2023).
autism (3 papers, 2017 to 2021). Persistent deficits in social interaction and communication and interaction as well as a markedly restricted repertoire of activity and interest as well as repetitive patterns of behavior. "The data implying there could be a lower association of some specific GATM gene variants with autism is an observation that would need to be corroborated in a larger group of autism patients, and with sub-populations of Asian ethnicities." (PMID 28758966, 2017). "Variants in GATM have not been associated with autism previously, nor has the chromosomal region of 15q21.1." (PMID 28758966, 2017). "There are no genes overlapping GATM that have been associated with autism." (PMID 28758966, 2017). "We sequenced GATM, GAMT and SLC6A8 genes in 166 patients with autism (coding sequence, introns and adjacent untranslated regions)." (PMID 28758966, 2017).
diabetes (3 papers, 2019 to 2022). "Likewise, reduced GATM expression levels were indicated to affect the development of diabetes in a murine diabetes model." (PMID 31819046, 2019). "Additionally, diabetes-associated genes such as RASGRP3, SIRPA, GATM and ESM1 were downregulated." (PMID 33923831, 2021).
epilepsy (3 papers, 2021 to 2025). A brain disorder characterized by episodes of abnormally increased neuronal discharge resulting in transient episodes of sensory or motor neurological dysfunction, or psychic dysfunction. "We aim to determine whether epilepsy can be considered part of the arginine:glycine amidinotransferase (AGAT) deficiency syndrome phenotype and to identify its associated electroclinical signatures." (PMID 40323733, 2025).
kidney failure (3 papers, 2021 to 2023). An acute or chronic condition that is characterized by the inability of the kidneys to adequately filter the blood. "GATM is highly expressed in the kidney tubule and mutation in the GATM gene causes a recessive disorder of creatine deficiency and the autosomal dominant Renal Fanconi syndrome, which includes kidney failure." (PMID 34071541, 2021).
renal Fanconi syndrome (3 papers, 2020 to 2024). "Another study revealed that intramitochondrial aggregates composed of mutated Glycine Amidinotransferase (GATM) protein are causative for an autosomal dominant form of renal Fanconi syndrome and CKD." (PMID 38807172, 2024).
colitis (2 papers, 2019 to 2023). Inflammation of the colon. "No significant protective effect of these two amino acids was observed, indicating that Arg supplementation inhibits colitis independently of the arginase/GATM/OAT metabolic pathway." (PMID 30972302, 2019). "Arginase and GATM are essential enzymes that exhibit important roles in colitis." (PMID 30972302, 2019).
colorectal cancer (2 papers, 2024 to 2025). A primary or metastatic malignant neoplasm that affects the colon or rectum. "Creatine may promote the metastasis of breast and colorectal cancer through enhancing Glycine amidinotransferase (GATM) activity and upregulating Snail (SNAI2) and Slug (SNAI1), which fostered cell migration in orthotopic mouse models." (PMID 40362760, 2025). "Consequently, targeting GATM or MPS1 presents a promising therapeutic strategy to inhibit cancer metastasis, particularly in colorectal cancers harbouring mutations in the transforming growth factor beta receptor." (PMID 39160643, 2024).
lupus nephritis (2 papers, 2025). Glomerulonephritis in the context of systemic lupus erythematosus. "A similar pattern was also observed for DDX5, B2M, and TMSB4X in CKD/lupus nephritis, and for GATM in the control group." (PMID 39974940, 2025).
melanoma (2 papers, 2021 to 2024). A malignant, usually aggressive tumor composed of atypical, neoplastic melanocytes. "After literature research, we chose 6 hub genes: ALDH2, ADH1B, ALDH3A2, DPT, EPHX2, and GATM, which were rarely reported in melanoma as the object of this research to explore their accuracy in the diagnosis and prediction of melanoma." (PMID 38378847, 2024). "Taken together, ALDH2, ADH1B, ALDH3A2, DPT, EPHX2, and GATM are potential biomarkers of melanoma, which have high prediction values for melanoma." (PMID 38378847, 2024).
renal fibrosis (2 papers, 2021 to 2025). A final common manifestation of a wide variety of chronic kidney diseases characterized by glomerulosclerosis and tubulointerstitial fibrosis. "Heterozygous GATM mutations have been observed to cause mitochondrial abnormalities and renal fibrosis caused by inflammasome activation." (PMID 40160460, 2025). "In contrast, mutations of GATM, an enzyme in the creatine biosynthetic pathway, leave ATP synthesis unaffected but do lead to mitochondrial protein aggregates, inflammasome activation, and renal fibrosis with progressive renal failure." (PMID 34349672, 2021).
acute myeloid leukaemia (1 paper, 2024). "A previous study revealed that GATM functions as a downstream factor in promoting the progression of FLT3‐ITD‐mutant acute myeloid leukaemia by regulating de novo creatine biosynthesis." (PMID 39160643, 2024).
age-related macular degeneration (1 paper, 2022). Age-related loss of vision in the central portion of the retina (macula), secondary to retinal degeneration.
allergic asthma (1 paper, 2022). A asthma with a basis in a pathological type I hypersensitivity reaction. "Our study uncovers a previously uncharacterized role for the de novo creatine biosynthesis enzyme GATM in M2 macrophage polarization, which may be involved in the pathogenesis of related inflammatory diseases such as an T helper 2 (Th2)-associated allergic asthma." (PMID 36177049, 2022).
asthma (1 paper, 2022). "The expression of GATM was positively associated with M2 macrophages in the BALF of HDM-induced asthma model mice." (PMID 36177049, 2022). "Based on this, we speculate that GATM expression increases in asthma may also be due to Th2-type immune-factor stimulation." (PMID 36177049, 2022). "Overall, our present study suggests that GATM may contribute to the progression of asthma via modulation of M2 macrophage polarization." (PMID 36177049, 2022). "Therefore, GATM is involved to some extent in the development of asthma." (PMID 36177049, 2022). "To link GATM expression with disease condition, we generated an acute HDM-induced murine model of asthma as a proxy for the acute inflammatory phenotype found in humans." (PMID 36177049, 2022). "We found that GATM was significantly expressed in the mouse asthma model, but not GAMT and slc6a8." (PMID 36177049, 2022).
brain tumours (1 paper, 2021). "Interestingly, expression of ASL, GATM, ODC, SLC25A13 and SLC25A15 is increased in tumours compared to normal brain tissue, indicating that the arginine biosynthesis pathway could be highly active in human brain tumours." (PMID 33809510, 2021).
creatine synthesis disorders (1 paper, 2025). "Guanidinoacetate methyltransferase (GAMT) deficiency and l-arginine:glycine amidinotransferase (AGAT) deficiency are autosomal recessive creatine synthesis disorders that result in CCDS." (PMID 40078706, 2025).